PCID2 (PCI domain containing 2)
Description:
Required for B-cell survival through the regulation of the expression of cell-cycle checkpoint MAD2L1 protein during B cell differentiation (By similarity). As a component of the TREX-2 complex, involved in the export of mRNAs to the cytoplasm through the nuclear pores. Binds and stabilizes BRCA2 and is thus involved in the control of R-loop-associated DNA damage and transcription-associated genomic instability. Blocks the activity of the SRCAP chromatin remodeling complex by interacting with SRCAP complex member ZNHIT1 and inhibiting its interaction with the complex (By similarity). This prevents the deposition of histone variant H2AZ1/H2A.Z at the nucleosomes of key lymphoid fate regulator genes which suppresses their expression and restricts lymphoid lineage commitment (By similarity).
Synonyms: FLJ11305
Tractability: PROTAC: ubiquitination databases record sites on it; its protein half-life has been measured.
Gene: Protein-coding gene on chromosome 13 (113,177,536 to 113,208,715, reverse strand). Ensembl gene ENSG00000126226.
Subcellular location: Cytoplasm; Nucleus, nuclear pore complex
Subcellular location (Human Protein Atlas): Nucleoli; Nucleoplasm
Gene Ontology:
Molecular function: protein binding; double-stranded DNA binding; RNA binding
Biological process: poly(A)+ mRNA export from nucleus; mRNA export from nucleus; negative regulation of gene expression, epigenetic; negative regulation of lymphoid progenitor cell differentiation; positive regulation of transcription by RNA polymerase II; post-transcriptional tethering of RNA polymerase II gene DNA at nuclear periphery; spleen development; transcription elongation by RNA polymerase II; positive regulation of B cell differentiation
Cellular component: cytoplasm; nuclear pore nuclear basket; nucleoplasm; nucleus; transcription export complex 2; nuclear pore; protein-containing complex
Genetic constraint (gnomAD): Loss-of-function variants: 15 observed, 19.67 expected, observed/expected ratio (o/e) 0.76, 90% interval 0.51 to 1.17. The upper end of that interval is the gene's LOEUF score, 1.17, which puts it in group 5 of 6, group 1 being the genes least tolerant of losing a copy. Missense variants: 167 observed, 218.57 expected, observed/expected ratio (o/e) 0.76, 90% interval 0.67 to 0.87. Synonymous variants: 98 observed, 87.79 expected, observed/expected ratio (o/e) 1.12, 90% interval 0.95 to 1.32.
Homologues: Orthologues: chimpanzee PCID2 (100% identical), macaque PCID2 (99% identical), guinea pig PCID2 (97% identical), mouse Pcid2 (97% identical), chimpanzee PCID2 (95% identical), dog PCID2 (95% identical), rat Pcid2 (93% identical), pig PCID2 (92% identical), rabbit PCID2 (92% identical), tropical clawed frog pcid2 (85% identical), zebrafish pcid2 (84% identical), Drosophila melanogaster PCID2 (49% identical), and 1 more.
Diseases named in the same sentence as PCID2 in open-access papers:
PCID2 is named in the same sentence as 11 diseases in open-access papers, as found by Europe PMC text mining. Sharing a sentence is not in itself a finding about the gene and the disease. The quoted sentences say what the papers report.
acute promyelocytic leukemia (1 paper, 2021). An aggressive form of acute myeloid leukemia (AML), characterized by arrest of leukocyte differentiation at the promyelocyte stage, due to a specific chromosomal translocation t(15;17) in myeloid cells. "Mechanistically, PCID2 physically associated with Promyelocytic leukemia protein (PML), the gene has been demonstrated to be involved in the development of acute promyelocytic leukemia (APL)." (PMID 34625711, 2021).
colon cancer (1 paper, 2022). "Only HSP90AB1, RIPK2, DDX21, UCHL5, GTPBP4, and PCID2 were significantly different in UC and COAD tissues, and they all showed overexpression in colon cancer tissues compared to UC tissues." (PMID 35372018, 2022).
colorectal cancer (1 paper, 2021). A primary or metastatic malignant neoplasm that affects the colon or rectum. "Using whole genome sequencing, PCI Domain Containing 2 (PCID2) was identified to be amplified in colorectal cancer (CRC)." (PMID 34625711, 2021).
colorectal tumor (1 paper, 2021). "PCID2 expression was examined in CRC cells and colorectal tumor tissues." (PMID 34625711, 2021).
HIV-1 infection (1 paper, 2024). The type species of lentivirus and the etiologic agent of acquired immunodeficiency syndrome (AIDS). "To further confirm the role of PCID2 on HIV-1 latency and specifically misregulation of HIV-1 vRNA splicing, we set out to investigate the effect of PCID2 depletion in a more physiologically relevant system for HIV-1 infection." (PMID 38384833, 2024).
liver cancer (1 paper, 2025). An epithelial or non-epithelial malignant neoplasm that arises from the liver. "This study not only support a rationale for further exploration of PCID2 as a therapeutic target in HCC but also provide valuable insights into the discovery of novel lead compounds from TCM for liver cancer treatment." (PMID 41394136, 2025).
tumor (4 papers, 2021 to 2025). "These reported findings indicate that PCID2 participates in diverse biological processes, including proliferation, apoptosis, stress response, and stemness, thereby contributing to tumor cell reprogramming and oncogenesis." (PMID 41394136, 2025). "Elevated PCID2 expression enhances malignancy, invasiveness, and metastatic potential, implicating PCID2 as a driver of cell cycle dysregulation and apoptosis resistance, thereby promoting tumor proliferation and invasion." (PMID 41394136, 2025). "Collectively, these findings highlight PCID2 as a critical regulator of tumor initiation and progression." (PMID 41394136, 2025). "When cells with elevated PCID2 expression were implanted in an in vivo model, an increased tumor weight and incidence of metastasis were observed, which further proved that PCID2 is an important factor in the tumorigenesis and progression of CRC." (PMID 39769375, 2024). "PCID2 promoted tumor growth in vivo through inducing cell proliferation and inhibiting apoptosis, as evidenced by Ki-67 and TUNEL staining, respectively." (PMID 34625711, 2021). "Mechanistic studies further revealed that PCID2 is frequently over-expressed in HCC tissues and correlates with tumor progression and poor prognosis." (PMID 41394136, 2025). "PCID2 mRNA and protein expression were higher in CRC cells and tumor tissues compared to healthy colonic tissues." (PMID 34625711, 2021). "Using co-immunoprecipitation and mass spectroscopy, we showed that PCID2 binds to promyelocytic leukemia (PML), a tumor suppressor involved in non-canonical β-catenin signaling." (PMID 34625711, 2021).
cancer (2 papers, 2021 to 2024). A tumor composed of atypical neoplastic, often pleomorphic cells that invade other tissues. "Cancer Pathway PCR array further validated the role of PCID2 in modulating expression of genes associated with cell adhesion, angiogenesis, migration, and invasion." (PMID 34625711, 2021). "CRC patients with overexpression of PCID2 had higher risk of cancer recurrence (P < 0.05)." (PMID 34625711, 2021). "Since advanced stage of CRC is more related with cancer recurrence, we further investigated the expression of PCID2 in different stages of CRC." (PMID 34625711, 2021). "Using whole genome sequencing, we identified PCI domain containing 2 (PCID2) as a novel gene amplified at 13q34 in cancer." (PMID 34625711, 2021). "PCID2 is located at 13q34, a genomic region with a higher frequency of amplification in CRC compared to other common cancer types." (PMID 34625711, 2021).
colorectal (1 paper, 2021). "PCID2 amplification is positively associated with its mRNA expression in CRC patients from our cohort and TCGA dataset, implying that copy number gain contributes to high PCID2 expression in colorectal carcinogenesis." (PMID 34625711, 2021). "We, therefore, hypothesized that PCID2 amplification could be an important mechanism for colorectal carcinogenesis." (PMID 34625711, 2021). "The up-regulation of PCID2 suppressed PML by promoting its UPS-mediated degradation, which in turn, releases β-catenin to engage canonical Wnt/β-catenin signaling, thus contributing to colorectal tumorigenesis." (PMID 34625711, 2021).
infection (1 paper, 2017). The state of being infected such as from the introduction of a foreign agent such as serum, vaccine, antigenic substance or organism. "We rescued Pcid2 in Pcid2−/− LT-HSCs via infection with Pcid2-overexpressing retrovirus." (PMID 29138493, 2017).
PCID2 also shares sentences with these, for which no sentence is quoted: hepatocellular carcinoma (1 paper).